MYC (MYC proto-oncogene, bHLH transcription factor)
Diseases named in the same sentence as MYC in open-access papers (continued):
Sharing a sentence is not in itself a finding about the gene and the disease.
cancer (continued). "Weak relationships were generally found across all the cancers, apparently inconsistent with a hypothesis that AURKA mRNA is a major target of hsa-let-7a unlike other oncogenes like RAS and MYC." (PMID 39527514, 2024). "Interestingly, reactivation of MYC, following the upregulation of NFATC4, partially inhibited the quiescent phenotype and failed to fully restore proliferative phenotype in cancer cells." (PMID 38418814, 2024). "Interestingly, although MYC regulates the expression of multiple glycolytic enzymes in cancer cells, FGF-MYC signaling preferentially controls the expression of HK2, not HK1 or other rate-limiting glycolytic enzymes in LECs." (PMID 38798921, 2024). "Of note, the WDR5 or G9a dependency was not dependent on MYCN amplification status, which is possible due to the high expression of c-Myc in MYCN non-amplified NB cell lines, while WDR5 and G9a have been shown to mediate c-MYC function in the other types of cancers." (PMID 37781575, 2023). "The cells of the non-TIC, bulk cancer regions were weakly positive for MSI2 and/or MYC." (PMID 37117191, 2023). "However, MYC expression induces anoikis resistance and non-adherent growth of MCF10A cells, both hallmarks of cancer." (PMID 36018850, 2022). "The experiments also demonstrated a co-occurrence of the activated TERT and DNA repair processes, and a co-activation of ALT and various oncogenic pathways, including E2F/DP1, MYC, YY1, ERK, NFκB, HIF1α and WNT, revealing that TERT inhibition alone is not enough to suppress cancer cells’ growth." (PMID 36615513, 2022). "Low oxygen tension may convert non-stem cancer cells into cancer stem cell-like status with increased self-renewing capacity as well as induction of essential stem cell factors, such as OCT4, Nanog, and c-MYC." (PMID 36014432, 2022). "It will be interesting to determine how neoplastic MYC, which does not remarkably require PARP activity in cisplatin-sensitive (i.e., early-stage) cancer cells, considerably depends on the PARP activity in cisplatin-resistant cancer cells." (PMID 34948122, 2021). "Although not present in the cell cycle map the MYC protein and its inhibitor MIZ1 have been included as this link may be relevant to the cancer cell context." (PMID 33975535, 2021). "This regulation does not require the presence of TERC, suggesting that TERT–MYC interaction on MYC-regulated promoters are independent of telomerase activity and could also explain why TERT and MYC levels are highly correlated in cancer cells." (PMID 33599797, 2021). "Despite the importance of the connection between deregulated MYC and BCL-2 pro-survival protein expression, and that the mechanisms by which they co-operate in cancer have been known for over two decades, there are still no clinically approved co-treatments that target both proteins." (PMID 33799592, 2021). "Overall, this demonstrates that the mechanism of resistance to BETi varies depending on cancer type, with LAC cells developing JQ1 resistance independent of MYC regulation, and identifying CK2 phosphorylation of BRD4 as a potential target to overcome resistance in this cancer." (PMID 33712563, 2021). "However, it is not known how MYC and TWIST1 work together to promote the metastasis of cancer cells." (PMID 31933479, 2020). "In addition to CT genes, BORIS participates in regulation of some non-CT genes such as BRCA1, Oct-3/4 (POU5F1), MYC, Rb2/p130, SBSN and hTERT (human telomerase reverse transcriptase) which are known to be involved in cancer progression." (PMID 30323717, 2018).
cancer (continued). "The products of many of these oncogenes—such as STAT3, KRAS, or MYC—are CCT substrates; hence, each patient whose cancer overexpresses CCT could be treated without the need of molecular subtyping the downstream substrates." (PMID 29299146, 2017). "Because of a lack of therapeutically efficacious MYC inhibitors, we propose the inhibition of MYC downstream targets, in particular GLS1, as an effective strategy to overcome acquired tolerance and resistance of cancer cells to CDK4/6 inhibitors." (PMID 28978620, 2017). "Here we used two oncogenes, c-MYC and BCL-2, as examples of co-localization of non-B DNA-forming sequences with genetic instability hotspots, because they are commonly involved in chromosomal translocations and the breakpoints in human cancer characterized." (PMID 27532010, 2016). "The majority of known driver gene amplifications (e.g., EGFR, ERBB2, MET, and MYC) and homozygous deletions (e.g., CDKN2A, PTEN, and RB1) were captured, with 320 RACSs (38%) containing at least one known putative cancer driver gene, in addition to 531 RACSs (62%) without known driver genes." (PMID 27397505, 2016). "Here again, if we query cancer datasets, CHEK1/CDK being cell-cycle regulators, are seen overexpressed in most aggressive tumours (e.g. triple-negative breast cancers), and but are not necessarily mutually exclusive to MYC overexpression." (PMID 26427375, 2015). "In addition, Aid is also reported to generate point mutations and/or double strand breaks at non-Ig locus, for example BCL6, MYC, PIM1 and PAX5, which are related to the cancer genesis." (PMID 24718089, 2014). "For example, the activities of many transcription factors regulating their targets depend on other modulators; MYC activates ATM to promote apoptosis and suppress tumorigenensis; whether RAF1 influences the cancer prognosis or not relies on HRAS." (PMID 24637666, 2014). "Reflecting these results back to the OI-MET model, we found that binding motifs for the TF pair AP1/MYC are more frequent than expected and that the AP1/MYC pair is significantly enriched in binding in cancer models, relative to non-cancer models, in these promoters." (PMID 24612742, 2014). "However, we did not notice substantial differences in ROS levels between MYC- dependent cancer cells and their differentiated counterparts and PIETC or BSO did not have any selective killing of MYC-dependent cancer cells." (PMID 24280108, 2013). "However, this does not provide an explanation for the induction of MYC targets by GCN2 inactivation, unless GCN2 has a hitherto unknown inhibitory effect on MYC in some cancer cells." (PMID 40032489, 2025). "However, the peroxisome pathway was not enriched in the MYC-driven NEJF10 cells in either culture condition, suggesting that peroxisome-mediated lipid metabolism might not be essential to MYC-driven cancer." (PMID 38853928, 2025). "Here, we inhibited MYC in CCA cells (KKU-M213 and RBE) using a small-molecule inhibitor before subjecting them to CAR-T cells to assess any cytotoxic effect the inhibitor may have on the cancer cells itself, and to determine non-lethal concentration ranges." (PMID 39766097, 2024). "This study suggests that targeting the IRF4-c-MYC axis, which remains challenging due to the lack of clinically useful targeted treatments, may offer novel therapeutic approaches not only for MM but also for other c-MYC-dependent cancer types." (PMID 38792604, 2024). "Notably, in all investigated cancer types, high SAMD1 expression correlates with high expression of MYC target genes, independent of whether high SAMD1 expression is favorable or unfavorable, suggesting that this feature is not predictive." (PMID 39137238, 2024).
cancer (continued). "Interestingly, when siRNA was used to knock down PVT1, low levels of c-Myc were found without significant changes in MYC mRNA levels, which indicates that c-Myc levels are closely related to PVT1 in high-copy 8q24 proliferating cancer cells." (PMID 31309249, 2019). "Interestingly, we did not observe transcriptional regulation of MYC and its target genes, a gene-expression response that is frequently used as a marker for BET inhibition in cancer highlighting the context-dependent effect of BET inhibitors in different tissue types." (PMID 31015424, 2019). "In this study, the authors show that MYC, but not MYCN or MYCL, represses BCL2, resulting in cells that are uniquely sensitive to apoptosis, and find that CHK1 and AURKA inhibitors may be useful for treating these cancers." (PMID 31375684, 2019). "Moreover, with MYC expression data obtained before rather than during treatment, KRAS WT but not KRAS mutant cancer cells can be classified in terms of whether they would be sensitive or resistant to cytotoxic drugs." (PMID 28152508, 2017). "However, the oncogenic transcription factor MYC also localizes to the POLR3G gene promoter in multiple cell lines and cancer contexts, presumably in the absence of OCT4 and NANOG, suggesting Pol III identity may be shaped by a distinct transcription factor repertoire in disease contexts." (PMID 37894362, 2023). "Notably, the data suggest that MYC synthetic lethality is not necessarily contingent on simultaneous overexpression of both targets but rather, endogenous levels of molecular nodes such as BRD4 and CHK1 become critical to the survival of MYC‐addicted cancer cells." (PMID 36684069, 2023). "Consequently, EGFR was lowly expressed in the cancer group versus the normal group in LUAD without a statistical difference (P-value: 0.19) and this expression pattern was similar to ESR1 (P-value: 0.42), MYC (P-value: 0.067), RELA (P-value: 0.058) and SMAD3 (P-value: 0.13)." (PMID 33506873, 2021).
infection (210 papers, 2004 to 2025). The state of being infected such as from the introduction of a foreign agent such as serum, vaccine, antigenic substance or organism. "We transfected urine cells with SeV encoding OCT3/4, SOX2, KLF4, and c-MYC and found that human embryonic stem cell-like colonies first appeared 5 to 8 days after infection." (PMID 31412925, 2019). "Lentiviral vectors encoding human OCT4, SOX2, KLF4 and c-MYC, at an approximate multiplicity of infection of 5 each, transduced early passage human keratinocytes (HK cells) derived from 56 to 78 year-old individuals with or without T2D." (PMID 22308265, 2012). "In a series of elegant experiments, E4orf1 was identified to be a significant HAdV protein responsible for upregulating MYC expression during infection and contributing to the associated increases in glycolysis and glutaminolysis observed in HAdV-infected cells." (PMID 34066504, 2021). "Other pathways with significant time × severity interactions included “KRAS signaling” and “MYC targets” in B cells, likely reflecting time-dependent changes in their proliferation during infection that vary according to severity." (PMID 40532694, 2025). "HAdV and HPV both act on the MYC promoter to upregulate its expression and also downregulate Myc copies, supposedly to aid in the latency of the infection." (PMID 40143226, 2025). "Interferes with the oncogenic capacity of MYC and its binding to calmodulinProteomics analysis of Hela cells infection with Salmonella revealed that Basp1 is one of Salmonella ubiquitin ligase SlrP on host cells." (PMID 41250600, 2025). "Infection increased the expression of Myc and MYC-dependent genes, predicted to affect all cellular compartments." (PMID 40000737, 2025). "All four methods found upregulation of the mTORC1 signaling, MYC targets V1, oxidative phosphorylation, ROS, allograft rejection, and both interferon pathways in the active infection group of the alveolar cells." (PMID 38981682, 2024). "In contrast, other Wnt-induced targets (CCND1, FN1, MCT1, MYC) were significantly downregulated by the infection." (PMID 38584257, 2024). "Further, 3-phosphoinositide-dependent protein kinase one signaling is evoked by the infection leading to the stabilization and phosphorylation of MYC." (PMID 35480118, 2022). "BAG1+ cells in the HR-IvL subset showed infection-triggered altered transcription and upregulated E2F target pathways with higher expression levels of c-Myc, along with a higher enrichment score for the MYC_Targets_V1 pathway." (PMID 35372115, 2022). "EBNA2, the only EBV oncoprotein required for newly infected B cell outgrowth over the first 8 days of in vitro infection, is required for glycolytic enzyme induction, likely together with MYC." (PMID 35108325, 2022). "Reprogramming was performed using a stoichiometric ratio-based infection of equivalent amounts of retroviruses encoding a POU5 protein (mOct4, X91 or X25) and the three factors KLF4, SOX2, and c-MYC." (PMID 36130934, 2022). "The levels of both E2F1 and MYC were increased in KO male mice in the presence of SP-A2 (1A0) protein rescue at the time of infection, even though most (except miR-378-3p, in KO male mice) of the miRNAs that target these genes were decreased in both sexes." (PMID 35844510, 2022). "This MYC-regulated switch between the latent and lytic phases of infection is a parallel between KSHV and EBV infections." (PMID 34066504, 2021). "The MYCBP gene, which controls the transcriptional activity of the proto-oncogene MYC and that plays a role in cell cycle progression, apoptosis and cellular transformation, was the only gene down-regulated in common to all infection settings." (PMID 33503840, 2021). "Recent advances in proteomics have identified that HAdV consistently upregulates MYC throughout infection." (PMID 34066504, 2021).
infection (continued). "Here, we demonstrated that lonidamine enhances the infection and tumoricidal effect of M1 virus by inhibiting MYC, a commonly overactivated oncogene." (PMID 33292203, 2020). "Instead, the decrease in cMYC level at 72 hpi correlates with the downregulation in MYC expression reported during infection." (PMID 32353058, 2020). "This infection participates in the regulation of MYC expression, which is necessary to gastric carcinogenesis occur, but its infection alone is insufficient to the disease establishment." (PMID 32150871, 2020). "We found that the modified virus improved the survival of the well-characterized MYC/Runx2 mouse compared to infections with the wild-type MLV." (PMID 31815961, 2019). "During an adenovirus E4ORF1 infection, anabolic glucose metabolism is promoted by virus-induced MYC activation and supports viral replication." (PMID 29601508, 2018). "Induction of MYC peaked at 19.6-fold 2 days after infection, while induction of ICAM and EZH2 was only 2.1- and 3.6-fold, respectively." (PMID 30487153, 2018). "As expected, WhiB4 overexpression increased the sensitivity of MYC 431 toward AG treatment at 4 weeks post-infection." (PMID 28548640, 2017). "Fibroblasts from the CLN5 patient were reprogrammed by the expression of SOX2, OCT3/4, KLF4 and MYC after infection with a Sendai virus delivery vector, in order to produce integration-free CLN5Y392X iPSCs." (PMID 28468312, 2017). "Among the early infection markers, two networks (−log10p = 31 and −log10p = 15) centered on MYC and MET respectively were significant." (PMID 26214306, 2015). "These experiments revealed that EBV infection induced p16INK4a transcription in the first few days after infection – when EBNA2 transactivates directly (eg c-MYC) or indirectly (eg cyclin D2) inducers of cell cycle progression and hyperproliferation." (PMID 23436997, 2013). "The cell cycle is further impacted by MAZ’s interaction with MYC, which we suspect is involved in cell cycle arrest, since many of MYC’s target proteins were downregulated during infection." (PMID 22937776, 2012). "As early as 9 hours after infection with 50 MOI Ad-c-MYC, the intercellular ROS level, as detected by DCF method, was significantly increased relative to controls and by 24 hours it reached to about a 30-fold increase." (PMID 20066163, 2009). "In addition, signaling pathways related to cell proliferation, like MYC_TARGETS_V1, E2F_TARGETS, and G2M checkpoint, appeared in the middle to late stages of infection (12 hpi to 48 hpi)." (PMID 38992966, 2025). "The other BCL-2 family gene upregulated during infection is CDK6, which facilitates cell cycle progression and is associated with c-MYC-induced cell proliferation and hence could counteract apoptosis." (PMID 39976440, 2025). "The results showed an increase in the proportion of stem cells in the S and G2/M phases, upregulation of proliferation-related genes, and activation of the Wnt pathway, evidenced by the elevated expression of Wnt target genes such as AXIN2, EPHB2, CCND1, CD44, TERT, and MYC following infection." (PMID 40396761, 2025). "Additionally, two lines of AC‐CTOSs derived from different patients both exhibited an “apical‐out” state of the apical membrane in Matrigel upon co‐culture with M2 macrophages and infection with lentiviruses overexpressing MYC." (PMID 39899538, 2025). "Network analysis identified that survival was associated with signaling networks of infection, immunity, epithelial-mesenchymal transition (EMT), hypoxia, glycolysis, focal adhesion, extracellular matrix, MYC signaling, autophagy and transcriptional regulation." (PMID 36575316, 2023). "In addition, in PdbLOX2-OE plants, JA-related genes, including AOC, AOS, OPR, COI, JAZ and MYC, showed significantly higher relative expression levels than in WT during infection but lower in PdbLOX2-IE plants." (PMID 36008749, 2022).